NPFFR1 (neuropeptide FF receptor 1)
Description:
Receptor for NPAF (A-18-F-amide) and NPFF (F-8-F-amide) neuropeptides, also known as morphine-modulating peptides. Can also be activated by a variety of naturally occurring or synthetic FMRF-amide like ligands. This receptor mediates its action by association with G proteins that activate a phosphatidylinositol-calcium second messenger system.
Synonyms: GPR147; NPFF1; OT7T022; NPFF1R1
Tractability: Small molecule: a high-quality ligand is known; it belongs to a druggable protein family. Antibody: UniProt places it where antibodies can reach, with high confidence; its Gene Ontology location is reachable by antibodies, with high confidence; UniProt predicts a signal peptide or a membrane-spanning region. PROTAC: a small molecule that binds it is known.
Target class: Membrane receptor; RF amide receptor; Family A G protein-coupled receptor; Peptide receptor (family A GPCR); Short peptide receptor (family A GPCR)
Gene: Protein-coding gene on chromosome 10 (70,247,329 to 70,284,004, reverse strand). Ensembl gene ENSG00000148734.
Subcellular location: Cell membrane
Pathways (Reactome):
Signal Transduction: G alpha (q) signalling events; Orexin and neuropeptides FF and QRFP bind to their respective receptors
Gene Ontology:
Molecular function: neuropeptide receptor activity; protein binding; G protein-coupled receptor activity
Biological process: neuropeptide signaling pathway; cellular response to hormone stimulus; G protein-coupled receptor signaling pathway
Cellular component: cilium; plasma membrane; 9+0 non-motile cilium; membrane
Genetic constraint (gnomAD): Loss-of-function variants: 17 observed, 12.07 expected, observed/expected ratio (o/e) 1.41, 90% interval 0.95 to 1.89. The synonymous counts are far from expectation, so gnomAD's model fits this gene poorly and the ratio says little. Missense variants: 604 observed, 530.57 expected, observed/expected ratio (o/e) 1.14, 90% interval 1.06 to 1.22. Synonymous variants: 296 observed, 233.16 expected, observed/expected ratio (o/e) 1.27, 90% interval 1.15 to 1.4.
Homologues: Orthologues: chimpanzee NPFFR1 (98% identical), macaque NPFFR1 (96% identical), pig NPFFR1 (89% identical), rabbit NPFFR1 (89% identical), guinea pig NPFFR1 (87% identical), mouse Npffr1 (87% identical), rat Npffr1 (87% identical), dog NPFFR1 (81% identical), tropical clawed frog npffr1 (66% identical), zebrafish npffr1 (42% identical), Drosophila melanogaster SIFaR (30% identical). Paralogues in human: NPFFR2 (48% identical), HCRTR2 (31% identical), HCRTR1 (30% identical), CCKAR (27% identical), CCKBR (24% identical), GALR1 (23% identical), GALR3 (23% identical), QRFPR (23% identical), FFAR4 (18% identical), AVPR1B (17% identical), OXTR (17% identical), AVPR2 (17% identical), and 4 more.
Diseases named in the same sentence as NPFFR1 in open-access papers:
NPFFR1 is named in the same sentence as 8 diseases in open-access papers, as found by Europe PMC text mining. Sharing a sentence is not in itself a finding about the gene and the disease. The quoted sentences say what the papers report.
Anxiety (6 papers, 2015 to 2025). Intense feelings of nervousness, tension, or panic often arise in response to interpersonal stresses. "Amphetamine withdrawal evoked anxiety-like behavior in rats, which was reversed with the central addition of NPFFR1/2 antagonist RF9." (PMID 38994950, 2024). "NPFFR1 plays a pivotal role in modulating stress and anxiety responses." (PMID 39405331, 2024). "Other RFamide peptides, including neuropeptide AF, neuropeptide SF and RFamide related peptide also target NPFFR1 or NPFFR2, and have been reported to activate the HPA axis and induce anxiety- or depression-like behaviors." (PMID 28825666, 2017). "Importantly, chronic infusion of the NPFFR1 antagonist GJ14 induced anxiolytic effects, and coinfusion of RFRP-3 and GJ14 reversed the effects of RFRP-3 on anxiety-like behavior." (PMID 38994950, 2024). "There is a growing body of evidence describing the involvement of RFamide peptides in controlling anxiety-related behaviors and HPA axis activity, but the roles for NPFFR1 and NPFFR2 remain unclear." (PMID 28825666, 2017).
prostate carcinoma (1 paper, 2023). A carcinoma that arises from epithelial cells of the prostate gland. "S1PR3 expression level was higher in AA than EA prostate cancer patients whereas GALR1, CHRM3, and NPFFR1 expression level was lower in AA than EA prostate cancer patients." (PMID 36937425, 2023).
NPFFR1 also shares sentences with these, for which no sentence is quoted: depression (2 papers); Hyperglycemia (1); Hypoglycemia (1); Obesity (1); osteoporosis (1); Testicular Dysfunction (1).